EGFR (epidermal growth factor receptor)
Diseases named in the same sentence as EGFR in open-access papers (continued):
Sharing a sentence is not in itself a finding about the gene and the disease.
adenocarcinoma (continued). "Adenocarcinoma in particular has the most identified actionable mutations, as evidenced by the approval of multiple targeted therapies directed against EGFR, ALK, ROS1, BRAF V600 and NTRK aberrations." (PMID 35621648, 2022). "Well-established actionable targets in adenocarcinoma include mutations in the gene encoding epidermal growth factor receptor (EGFR, 9%), anaplastic lymphoma kinase (ALK, 3.9%), c-ros oncogene 1 (ROS1, 1%) and B-type Raf proto-oncogene (BRAFV600E, 1%)." (PMID 35743191, 2022). "Very few data are available on the association between adenocarcinoma subtypes and responses to EGFR-TKIs." (PMID 34652430, 2022). "The effect of exosomes isolated from patients with an Epidermal Growth Factor Receptor (EGFR)-mutated adenocarcinoma on the promotion of epithelial–mesenchymal transition (EMT) and invasion were examined." (PMID 35954442, 2022). "A number of researches have shown that the incidence of EGFR mutation is higher in women, non‐smokers, and adenocarcinoma." (PMID 35081265, 2022). "Comprehensive histopathological and molecular evaluation revealed that EGFR mutations were frequent in adenocarcinomas (p < 0.001) with a predominant acinar pattern (p < 0.001)." (PMID 35740676, 2022). "Due to its origin in the bloodstream, adenocarcinoma has multiple primaries, with EGFR mutations associated with HPV." (PMID 35847783, 2022). "EGFR mutation was frequently detected in tumors located in the upper portion of the lung (79/113; 69.9%) and was common in adenocarcinoma (111/113; 98.2%), especially in tumors with an acinar-predominant pattern (85/113; 76.6%)." (PMID 35740676, 2022). "Among patients with advanced adenocarcinoma containing EGFR mutations that received TKIs between 1 January 2008 and 31 December 2020, 259 were retrospectively reviewed." (PMID 35330404, 2022). "It was stated by the authors that adenocarcinomas with an EGFR-mutation can transform into SCLC in the process of acquiring resistance to EGFR tyrosine kinase inhibitors." (PMID 35677534, 2022). "Specifically, while EGFR mutations occur in approximately 15% of adenocarcinoma NSCLC in Caucasian populations in Canada, USA and Europe, this mutation is far more frequent in the East Asian population, with a prevalence of 40–50%." (PMID 35621648, 2022). "The frequencies of driver mutations in the early stages were equivalent to those in advanced stages, i.e., the rates of EGFR mutations in adenocarcinomas were 12.7% (72/567) and 12.0% (78/650) in early and advanced NSCLC, respectively (p = 0778)." (PMID 36293366, 2022). "The incidence of epidermal growth factor receptor (EGFR) mutations among Asian patients with adenocarcinoma is approximately 51.4%." (PMID 36192767, 2022). "All adenocarcinoma patients underwent genetic testing, 75 of who had EGFR mutation, and 3 had ALK mutation." (PMID 36615124, 2022). "Improvements in histological classifications and diagnostic techniques, especially of adenocarcinoma in concert with the identification on specific oncogenic factors (EGFR mutations or rearrangements of the ALK) have been suggested to affect their increase." (PMID 34857781, 2021). "In adenocarcinoma, several driver mutations have been identified, including mutations/alterations of the epidermal growth factor receptor (EGFR), anaplastic lymphoma kinase (ALK), and ROS1, among others; most of them are therapeutically targetable." (PMID 33659043, 2021). "Considering that EGFR mutations are more common in adenocarcinomas and our cohort reported more than 90% of EGFR mutations in adenocarcinoma." (PMID 33956842, 2021). "Seventy-seven patients met the Eastern Cooperative Oncology Group (ECOG) performance status (PS) criteria of 0–1, and all patients had adenocarcinoma histology harboring the EGFR T790M mutation." (PMID 34359582, 2021).
adenocarcinoma (continued). "Our results show that the frequency of EGFR mutations at the initial testing among all patients and those with adenocarcinoma was 32.5% versus 33.3% and 42.2% versus 41.9% for Therascreen versus Cobas, respectively." (PMID 33528892, 2021). "A systematic review of 27 studies reported that the EGFR mutation rate was the highest in lepidic predominant adenocarcinoma (LPA) (50.7%), while SPA (p < 0.01) and invasive mucinous adenocarcinoma (IMA) (p < 0.01) were associated with the EGFR-wild status." (PMID 35049681, 2021). "Aberrant activation of PI3K/AKT/mTOR pathway is one of the mechanisms of acquired resistance to EGFR-TK inhibitors in patients with adenocarcinoma carrying EGFR activating mutations." (PMID 33997043, 2021). "A single EGFR mutation was a good prognostic marker, but EGFR/CTNNB1 co-mutations showed a significantly shorter RFS even for stage I adenocarcinoma, most of which were cured." (PMID 33140254, 2021). "We also explored the difference in clinical and CT features between EGFR exon 21- and 19-mutated adenocarcinomas." (PMID 33707479, 2021). "The decision for systemic therapy of stage IV NSCLC patients usually depends on performance score (PS) 0–1, adenocarcinoma, presence of EGFR mutation, and age 18–75." (PMID 34993132, 2021). "EGFR mutations have been proved to be relevant to NSCLC adenocarcinomas as a predictive biomarker for the tyrosine kinase inhibitors (TKIs) therapy in EGFR-mutant patients." (PMID 33906297, 2021). "In this study, all patients were adenocarcinoma with sensitive EGFR mutations, 98% had a relatively good ECOG PS score of 0-1 and the median age of all patients was 58 years, which made the results of this study comparable to LUX-Lung 3 and 6 trials." (PMID 34048189, 2021). "EGFR mutations can be detected in 15% of adenocarcinoma subtype of Caucasian NSCLC but in 40–50% of same subtype of East Asian NSCLC." (PMID 34257561, 2021). "In East Asian studies, approximately half of the adenocarcinoma patients were found to harbor EGFR mutations." (PMID 33305905, 2021). "We investigated the distribution of the number of genetic alterations in resected EGFR-mutated adenocarcinoma." (PMID 34298845, 2021). "Patients with de-novo EGFR-mutated SCC tend to have a shorter PFS than their adenocarcinoma counterparts." (PMID 34572868, 2021). "Various studies show the predisposition for brain involvement in EGFR mutated adenocarcinoma, this being present at diagnosis in 25% of patients and developing at 3 years in approximately 50% of cases." (PMID 34465283, 2021). "The frequency of uncommon mutations among EGFR mutation‐positive adenocarcinoma cases (7.0% [9/128] in Therascreen and 4.6% [7/153] in Cobas) was not significantly different." (PMID 33528892, 2021). "The frequencies of del19 and L858R among EGFR mutations in adenocarcinoma were 39.8% and 53.1% in the Therascreen group and 52.3% and 43.1% in the Cobas group, respectively." (PMID 33528892, 2021). "The review of two cases harboring EGFR mutations (case 8 and case 10) showed admixed non‐small‐cell and small‐cell features, suggestive of de novo small‐cell transformation of EGFR‐mutated adenocarcinomas." (PMID 32191822, 2021). "As reported, the epidermal growth factor receptor (EGFR) mutation is one of the most common mutated genes detected in adenocarcinoma." (PMID 34136375, 2021). "The most common histology was adenocarcinoma and activating EGFR mutations or ALK translocations were seen in 31% and 4%, respectively." (PMID 34145985, 2021).
adenocarcinoma (continued). "KRAS G12A somatic point mutation in adenocarcinomas is categorized clinically as ineligibility criteria for anti-epidermal growth factor receptor (EGFR) monoclonal antibody therapies." (PMID 33652552, 2021). "In this study, we retrospectively recruited advanced lung SCC patients with EGFR mutations, and enrolled patients with EGFR-mutant adenocarcinoma and EGFR wild-type SCC." (PMID 34195081, 2021). "Comparison of the genomic profiles revealed that EGFR-mutant SCC patients had similar mutation characteristics to EGFR-mutant adenocarcinoma patients, but differed from those with EGFR wild-type SCC." (PMID 34195081, 2021). "Out of 1967 adenocarcinoma tumors, the EGFR and ALK mutational status was respectively known for 717 (36.4%) and 245 (12.4%) cases." (PMID 34016641, 2021). "EGFR genotyping at the initial diagnosis showed Del 19 and L858R mutations in 42 (55.3%) and 34 (44.7%) of these patients with adenocarcinoma." (PMID 34704378, 2021). "Some authors have found that EGFR mutation is a significant predictor of overall survival and relapse-free survival in surgically resected adenocarcinoma, while others showed that EGFR mutation was insignificant for post-surgical survival." (PMID 34249741, 2021). "Twenty-six patients with adenocarcinoma were examined for EGFR mutation from tissue biopsy, peripheral blood sample and bronchoalveolar lavage." (PMID 34040898, 2021). "The major histological type was adenocarcinoma (90.6%), and 70 (38.9%) patients were EGFR mutation-positive." (PMID 34447289, 2021). "The EGFR mutations consider a potential therapeutic target, which is more frequent in adenocarcinomas (ADC) patients and less common in squamous cell carcinoma (SCC)." (PMID 33639678, 2021). "Patient 7 was a female with adenocarcinoma harboring an EGFR exon 21 mutation (L858R) and had extensive brain metastases." (PMID 33473101, 2021). "Patients with adenocarcinoma with EGFR mutation who underwent rebiopsy and were treated with EGFR‐TKIs were included." (PMID 33529490, 2021). "Almost 99% of residents in Taiwan are covered by the Taiwan National Health Insurance and only adenocarcinoma harboring susceptible EGFR mutations is reimbursed." (PMID 33941115, 2021). "EGFR gene mutations were observed commonly in female, <60 years, and adenocarcinoma patients with NSCLC in previous reports." (PMID 33997043, 2021). "The analysis of EGFR mutations is important for the diagnosis and treatment decision in NSCLC, especially adenocarcinoma, as EGFR mutations are a potential predictive biomarker for the EGFR-TKI therapy response." (PMID 33639678, 2021). "Among the 99 adenocarcinoma patients, epidermal growth factor receptor (EGFR) mutations were detected in 75 patients (75.8%), and ALK rearrangement was found in eight patients (8.1%)." (PMID 34435141, 2021). "Due to the limited size of the patient sample, the prevalence of adenocarcinoma and EGFR mutations deviates to a certain extent from established data." (PMID 34040898, 2021). "We believe this work is the first NGS study focusing on resected EGFR-mutated adenocarcinoma that compared recurrence rates." (PMID 34298845, 2021). "On the scale of Saudi Arabia, Levant region and internationally (China and Caucasian population), adenocarcinoma was found to be the subtype associated with the highest numbers of EGFR mutations." (PMID 34963835, 2021). "Among these, mutations in the epidermal growth factor receptor (EGFR) are present in around 15% of adenocarcinomas and represent the target for first-, second- and third-generation tyrosine kinase inhibitors (TKIs), all usable in clinical practice." (PMID 34680416, 2021). "Brain metastases occur in 20% to 32% of patients diagnosed with NSCLC, most frequently in patients with adenocarcinomas and tumors harboring EGFR mutations or ALK rearrangements with an incidence of up to 72%." (PMID 34181677, 2021).
adenocarcinoma (continued). "The majority of earlier reports have suggested that EGFR protein expression and/or EGFR gene copy number gain are associated with shorter survival of gastroesophageal cancers including adenocarcinomas and ESCCs." (PMID 33169187, 2021). "In previous reports of transformation to SCLC in EGFR-mutant adenocarcinoma, the EGFR mutation was identical in all the transformed SCLC tissue." (PMID 34094904, 2021). "The predictive power of EGFR mutations (representing 17% of the adenocarcinoma patients) was discovered in 2004." (PMID 33519934, 2021). "For early-stage resectable adenocarcinoma, the detection is less important, whereas for advanced-stage patients with EGFR mutations, TKIs are the first-line standard modality for the treatment today, so the detection is urgently needed." (PMID 32082997, 2020). "We developed and validated a radiomics signature-based nomogram for the non-invasive detection of EGFR mutations in patients with advanced adenocarcinoma through preprocessing, parameters screening and model building from CT images." (PMID 32082997, 2020). "Most patients (n=32; 94.1%) had adenocarcinoma; 12 (35.3%) patients had confirmed EGFR mutation, while two (5.9%) had ALK translocation." (PMID 33033525, 2020). "Adenocarcinoma with EGFR mutation is reported to be associated with a higher incidence of GGN in comparison to adenocarcinoma with wild-type EGFR." (PMID 32571419, 2020). "Seven patients had adenocarcinoma of which one patient harbored the mutation for epidermal growth factor receptor." (PMID 31701630, 2020). "Adenocarcinoma subtype was the most common subtype in 85.7%, and 40% of the total cohort (73/196) had a positive EGFR mutational status." (PMID 33324556, 2020). "A total of 20 patients (median age: 69 years; 14 males; 20 adenocarcinomas; six epidermal growth factor receptor mutations) were enrolled in nine centers." (PMID 32421226, 2020). "We retrospectively investigated 117 untreated metastatic lung EGFR mutated adenocarcinoma patients with a PD-L1 immunohistochemistry test." (PMID 32092879, 2020). "Four patients with adenocarcinoma carried driver mutations (3 had an EGFR tyrosine kinase mutation and 1 had an ALK gene rearrangement)." (PMID 32252414, 2020). "Patients with lower lobe cancer had a lower proportion of adenocarcinoma histology and epidermal growth factor receptor (EGFR) mutations." (PMID 32913267, 2020). "Amplification Refractory Mutation System PCR (ARMS-PCR) was used to identify EGFR gene mutations in 889 cases of adenocarcinoma." (PMID 32429938, 2020). "Out of the 29 adenocarcinoma patients, 10 had active driver mutations, distributed into EGFR mutation (n = 9), and ALK rearrangement (n = 1)." (PMID 32767461, 2020). "A similar analysis of CEAIn expression and EGFR mutation status in adenocarcinoma patients (n = 517) revealed that serum CEAIn levels were higher in the EGFR-mutant than in the wild-type group." (PMID 32034239, 2020). "Patients with adenocarcinoma (P < 0.001) and peripheral tumors (P < 0.001) were found to be more likely to have EGFR mutations." (PMID 32729257, 2020). "The PAK1 and phospho-PAK1 levels were elevated in HCC827 (EGFR-mutated adenocarcinoma cell line) cells compared to those in A549 (EGFR wild-type cell line) or BEAS-2B (normal bronchial epithelial cell line) cells." (PMID 33261184, 2020). "Among adenocarcinomas, EGFR and KRAS mutations were present in 55.6% (15/27) and 22.2% (6/27) of tissue samples, respectively." (PMID 32196518, 2020). "EGFR mutations were detected more often in younger and female patients or patients with adenocarcinoma." (PMID 33255238, 2020).
adenocarcinoma (continued). "Among patients diagnosed with adenocarcinoma, mutational analysis was performed in 13 cases, one patient showed EGFR mutation, four patients KRAS mutation, while PD‐L1 expression was confirmed in three samples." (PMID 32401433, 2020). "Here, we present a report of a patient with adenocarcinoma harboring EGFR exon 19 deletion mutation treated with osimertinib as first‐line treatment." (PMID 32666714, 2020). "The sensitivity analysis of the patients diagnosed with adenocarcinomas showed that the percent of association mediated was 18.8% through EGFR mutations alone, and this indirect association was statistically significant (P = 0.021)." (PMID 32913267, 2020). "HER2 alteration has been reported to be more common in women, non‐smokers, Asians and patients with adenocarcinomas, which is similar to those with EGFR mutation." (PMID 32729257, 2020). "On the basis of that, we found EGFR mutations were more common in females, younger age groups, and well-differentiated adenocarcinoma." (PMID 32429938, 2020). "EGFR activating mutation frequency in stage IV adenocarcinoma was higher (p=0.02) in women (33.9%) than in men (16.4%)." (PMID 33084767, 2020). "Subsequently, we further conducted stratified analysis, finding that among the adenocarcinoma cases, patients with EGFR 19 deletion mutation have longer OS than the wide-type (36.0 months versus 19.0 months, p = 0.046)." (PMID 32047821, 2020). "In the sensitivity analysis for adenocarcinoma patients, EGFR mutations were also identified as a significant mediator." (PMID 32913267, 2020). "The vascular and pleural invasion and EGFR mutation were regarded as the more common features in STAS positive adenocarcinoma." (PMID 33505903, 2020). "This study first investigated clinical and prognostic features of advanced adenocarcinoma according to EGFR mutation status in Korean patients, particularly for specific EGFR mutation types (mutations in E18, E19, E20, and E21)." (PMID 32053675, 2020). "Age and disease status were associated with LMC in patients with EGFR‐mutant adenocarcinoma, and EGFR‐TKI, Ommaya reservoir, and good performance status were related to survival benefit." (PMID 31910497, 2020). "EGFR mutations are commonly detected in adenocarcinoma, with higher rates amongst Asians (38.8%–64.0%) than amongst Caucasians (4.9%–17.4%)." (PMID 32053675, 2020). "Adenocarcinoma (n = 95, 91.3%) was the dominant histology and 42 (40.4%) patients had targetable mutations (EGFR mutation – 37, EML4-ALK gene fusion – 5)." (PMID 32176106, 2020). "High expression of miR-155 and miR-222 are poor prognoses, especially high miR-222 found in metastasis M1b and positive EGFR mutation and miR-155 found in adenocarcinoma and positive EGFR gene mutations." (PMID 32283582, 2020). "We found that the amount of EGFR mutations was significantly higher in female adenocarcinoma patients than in male, which was also supported by the data from PIONEER study." (PMID 32429938, 2020). "ROS1-rearranged adenocarcinomas appeared as solid tumors and were associated with young age, pericardial metastases and advanced nodal metastases relative to tumors with EGFR mutations or ALK rearrangement." (PMID 33005033, 2020). "The high expression of miR-222 and miR-155 was found as poor prognosis especially in M1b metastasis, adenocarcinoma cell type and positive EGFR gene mutation cases." (PMID 32283582, 2020). "This study identified 142 patients with EGFR-mutated adenocarcinoma who underwent definitive therapy compared to 140 EGFR-wildtype controls." (PMID 32523650, 2020). "Adenocarcinoma with epidermal growth factor receptor (EGFR) gene mutation accounted for 38.0% (46/121), and phase IV disease accounted for 83.6% (138/165) of all patients." (PMID 32191394, 2020). "For instance, EGFR tyrosine kinase inhibitors (TKIs) being the first line treatment of choice for adenocarcinoma patients, T790M mutation is the major mechanism of acquired resistance." (PMID 32564237, 2020).